IGFBP7 (insulin like growth factor binding protein 7)
Description:
Binds IGF1 and IGF2 with a relatively low affinity. Stimulates prostacyclin (PGI2) production. Stimulates cell adhesion. Acts as a ligand for CD93 to play a role in angiogenesis.
Synonyms: IBP-7; IGFBP-7; TAF; MAC25; PSF; FSTL2; AGM; IGFBP-7v; IGFBPRP1; RAMSVPS
Tractability: Antibody: its Gene Ontology location is reachable by antibodies, with high confidence; UniProt places it where antibodies can reach, with medium confidence; UniProt predicts a signal peptide or a membrane-spanning region. PROTAC: ubiquitination databases record sites on it.
Gene: Protein-coding gene on chromosome 4 (57,030,766 to 57,110,690, reverse strand). Ensembl gene ENSG00000163453.
Subcellular location: Secreted
Subcellular location (Human Protein Atlas): Golgi apparatus; Predicted to be secreted
Pathways (Reactome):
Metabolism of proteins: Post-translational protein phosphorylation; Regulation of Insulin-like Growth Factor (IGF) transport and uptake by Insulin-like Growth Factor Binding Proteins (IGFBPs)
Cellular responses to stimuli: Senescence-Associated Secretory Phenotype (SASP)
Gene Ontology:
Molecular function: protein binding; receptor ligand activity; extracellular matrix structural constituent; insulin-like growth factor binding
Biological process: angiogenesis; cell adhesion; negative regulation of cell population proliferation; regulation of signal transduction; cellular response to hormone stimulus; cellular response to prostaglandin E stimulus; embryo implantation; regulation of cell growth; regulation of steroid biosynthetic process; response to cortisol; response to retinoic acid; signal transduction
Cellular component: extracellular exosome; extracellular matrix; extracellular region; endoplasmic reticulum lumen; non-collagenous component of interstitial matrix
Genetic constraint (gnomAD): Loss-of-function variants: 21 observed, 16.08 expected, observed/expected ratio (o/e) 1.31, 90% interval 0.92 to 1.81. The synonymous counts are far from expectation, so gnomAD's model fits this gene poorly and the ratio says little. Missense variants: 373 observed, 296.01 expected, observed/expected ratio (o/e) 1.26, 90% interval 1.16 to 1.37. Synonymous variants: 170 observed, 121.31 expected, observed/expected ratio (o/e) 1.4, 90% interval 1.24 to 1.59.
Homologues: Orthologues: chimpanzee IGFBP7 (100% identical), macaque IGFBP7 (99% identical), pig IGFBP7 (93% identical), rat Igfbp7 (91% identical), mouse Igfbp7 (91% identical), guinea pig IGFBP7 (90% identical), zebrafish igfbp7 (49% identical). Paralogues in human: IGFBPL1 (41% identical), KAZALD1 (33% identical).
Diseases named in the same sentence as IGFBP7 in open-access papers:
IGFBP7 is named in the same sentence as 252 diseases in open-access papers, as found by Europe PMC text mining. Sharing a sentence is not in itself a finding about the gene and the disease. The quoted sentences say what the papers report.
acute kidney injury (99 papers, 2014 to 2026). Sudden and sustained deterioration of the kidney function characterized by decreased glomerular filtration rate, increased serum creatinine or oliguria. "The combination of urinary tissue inhibitor of metalloproteinase 2 (TIMP-2) and insulin-like growth factor-binding protein 7 (IGFBP7) ([TIMP-2]⋅[IGFBP7]) has emerged as a strong predictor of acute kidney injury (AKI), which is associated with poor outcomes." (PMID 39982587, 2025). "Urine IGFBP7 has been approved as a marker by the US Food and Drug Administration for determining the risk of developing moderate-to-severe acute kidney injury, indicating that PTCs in Statue 6 are injured and inflammatory PTCs." (PMID 38077419, 2023). "IGFBP7, also known as IGFBP-rP1, has been reported to be associated with several diseases, including cancer and acute kidney injury." (PMID 37304887, 2023). "It is noteworthy that TIMP2 IGFBP7 has been approved by the US Food and Drug Administration as an aid in the risk assessment for moderate or severe (stage 2–3) acute kidney injury within the next 12 h." (PMID 34641779, 2021). "Monitoring urine biomarkers, such as tissue inhibitor of metalloproteinases-2 (TIMP-2) and insulin-like growth factor-binding protein 7 (IGFBP-7), for acute kidney injury in high-risk patients may help guide interventions." (PMID 40843750, 2025). "Changes in the concentration of [TIMP-2] [IGFBP7] in urine after fluid resuscitation could be used to differentiate the risk of developing sepsis for patients with acute kidney injury." (PMID 38259686, 2023). "Diagnostic value of urinary TIMP-2 and IGFBP7 for acute kidney injury in individual studies." (PMID 31261582, 2019). "Insulin-like growth factor-binding protein 7 serves as a biomarker for sepsis-associated acute kidney injury (SA-AKI) and contributes to the pathophysiology of SA-AKI via dampening NIX-dependent mitophagy." (PMID 38374038, 2024). "The urinary tissue inhibitor of metalloproteinases-2 and insulin-like growth factor-binding protein 7 ([TIMP-2]∙[IGFBP7]) have been introduced to improve risk prediction of severe acute kidney injury (AKI) within 12 hours of measurement." (PMID 31712687, 2019). "TNF and TLR4 are involved in regulating immune responses during kidney injury, whereas IGFBP7 serves as a marker for acute kidney injury." (PMID 41567268, 2026). "We found that heat stress increased plasma creatinine and cystatin C, in addition to urinary IGFBP7 × TIMP‐2, collectively indicating a potential risk for acute kidney injury." (PMID 39417775, 2025). "They showed that IGFBP7 knockout ameliorates kidney dysfunction, inflammation and cell death in acute kidney injury models by binding to PARP1, inhibiting its degradation and mitigating tubular injury and inflammation." (PMID 40012220, 2025). "As research advances, IGFBP-7 is emerging as a potential biomarker for various diseases such as acute kidney injury, heart failure, and cancer." (PMID 39507055, 2024). "A recent study has reported that IGFBP7 exacerbates the pathological processes in the acute phase of inflammatory diseases, such as acute kidney injury and acute lung injury, and is one of the injury markers in acute kidney injury." (PMID 38840498, 2024). "The measurement of urinary levels of tissue inhibitor of matrix metalloproteinase 2 (TIMP-2) and insulin-like growth factor-binding protein 7 (IGFBP7), both function in promoting G1 cell cycle arrest, has demonstrated utility in predicting acute kidney injury." (PMID 38708150, 2024). "The urinary biomarker combination [TIMP-2] × [IGFBP7], which are both markers for G1 cell cycle arrest, has been identified and validated to predict moderate to severe acute kidney injury in critically ill patients earlier than other known biomarkers." (PMID 38673754, 2024).
acute kidney injury (continued). "In conclusion, TIMP-2 × IGFBP-7 is considered a more reliable indicator for predicting or diagnosing poor prognosis or even mortality in patients with acute renal failure following cardiac surgery." (PMID 38788006, 2024). "The cell cycle arrest biomarkers tissue inhibitor of metalloproteinase‐2 (TIMP‐2) and insulin like growth factor binding protein 7 (IGFBP7) have shown to be valuable biomarkers for early detection of acute kidney injury (AKI) in people." (PMID 38053473, 2023). "Such physiological and pathological mechanisms lead to increased urinary TIMP2 and IGFBP7 levels in acute kidney injury and their role in the early prediction of AKI." (PMID 37055509, 2023). "Studies have shown that IGFBP7 is important for clinical staging of sepsis-related acute kidney injury because IGFBP7 can delay the progression of acute kidney injury by inhibiting RNF4/PARP1-mediated tubular injury." (PMID 38259686, 2023). "The [TIMP-2] [IGFBP7] ratio (Nephrocheck®) has been recently applied in patients in intensive care units patients to predict the development of acute kidney injury." (PMID 35170890, 2022). "This study aimed to observe the role of urinary kidney injury molecule (KIM-1), interleukin (IL-18), and insulin-like growth factor-binding protein 7 (IGFBP-7) levels in predicting acute kidney injury (AKI) in children with sepsis." (PMID 36545669, 2022). "Advanced urinary injury markers for tubular (NGAL, DKK-3 and KIM-1) and glomerular damage (TIMP-2 and IGFBP-7) were recently introduced for monitoring acute kidney injury." (PMID 34640591, 2021). "It is worth noting that two markers which have attracted a lot of interest in the prediction of acute kidney injury, IGFBP-7 and TIMP-2, seem to be differently affected by TCEP reduction." (PMID 32111925, 2020). "Insulin-like growth factor binding protein 7 (Igfbp7), a cell cycle arrest biomarker, is released in the earliest stages of acute kidney injury, which has been suggested to be an important predictor of acute kidney injury following cardiac surgery." (PMID 30770755, 2019). "The urinary biomarkers TIMP-2 and IGFBP7, which are released in stressed cells as an “alarm signal” for adjacent cells, have recently been established as early predictors of imminent acute kidney injury (AKI) in general and postoperative patients." (PMID 29973233, 2018). "Tissue inhibitor of metalloproteinase-2 (TIMP-2) and insulin-like growth factor binding protein 7 (IGFBP7), inducers of G1 cell cycle arrest, are two recently discovered good biomarkers for early diagnosis of acute kidney injury (AKI)." (PMID 28340605, 2017). "We measured TIMP-2 and IGFBP7 and compared the results to acute kidney injury by RIFLE criteria for creatinine using area under the receiver operating characteristic curve (AUC)." (PMID 27245788, 2016). "In this experimental model of sepsis in the rat, cell cycle arrest biomarkers TIMP-2 and IGFBP7 are valid predictors of acute kidney injury." (PMID 27245788, 2016). "The cell cycle arrest biomarkers tissue inhibitor of metalloproteinases-2 (TIMP-2) and insulin-like growth factor-binding protein 7 (IGFBP7) have emerged as promising indicators for detecting acute kidney injury (AKI), particularly in critically ill patients and those undergoing cardiac surgery." (PMID 40807208, 2025). "Moreover, elevated IGFBP7 mRNA levels have been observed in uranium nitrate-induced acute renal failure in mice." (PMID 39081862, 2024). "In a prospective cohort trial of 557 adult patients undergoing cardiac surgery, urinary TIMP-2 combined with IGFBP-7 was an excellent early indication of cardiac surgery-associated acute kidney injury (CSA-AKI) and related short-term negative outcomes." (PMID 39001241, 2024). "IGFBP7 is the known urinary prognostic marker in early acute kidney injury." (PMID 33791193, 2020).
acute kidney injury (continued). "The presence of insulin in association with the IGF-I pathway demonstrated in our studies may indicate with some probability, that IGFBP-7 could be a potential biomarker of acute kidney injury in dogs with babesiosis." (PMID 31801572, 2019). "As a molecular marker of acute kidney injury, IGFBP-7 has attracted much attention." (PMID 31661774, 2019). "The capability of urinary TIMP-2 (tissue inhibitor of metalloproteinase) and IGFBP7 (insulin-like growth factor binding protein)—NephroCheck Test (NC) = ([TIMP-2] x [IGFBP7]) / 1000)—to predict renal recovery from acute kidney injury (AKI) has been poorly studied." (PMID 28085896, 2017). "IGFBP7 has been proposed as a biomarker for acute kidney injury (AKI), aiming to enhance early detection, discrimination, and prognosis assessment, complementing serum creatinine and urine output." (PMID 39081862, 2024). "Moreover, inhibition of PARP1 degradation due to insulin-like growth factor binding protein 7 could promote the development of acute kidney injury." (PMID 37773127, 2023). "IGFBP-7 is proven to be involved in the development of many diseases, including diabetes, obesity, acute kidney injury (AKI), and cancers." (PMID 35625639, 2022). "Can measuring the cell-cycle arrest biomarkers tissue inhibitor of metalloproteinases 2 (TIMP-2) and insulinlike growth factor binding protein 7 (IGFBP7) enhance acute kidney injury (AKI) staging using a recently proposed framework?" (PMID 35583867, 2022). "Insulin-like growth factor binding protein 7 (IGFBP-7) and tissue inhibitor of metalloproteinases 2 (TIMP-2), which are secreted soluble proteins as part of the uEV proteome, are of great interest as biomarkers to predict the risk of developing acute kidney injury (AKI)." (PMID 32111925, 2020). "The first FDA-approved test to assess risk for acute kidney injury (AKI), [TIMP-2]•[IGFBP7], is clinically available in many parts of the world, including the USA and Europe." (PMID 31221200, 2019). "Valuable biomarkers indicative of acute kidney injury (AKI) are insulin-like growth factor-binding protein 7 (IGFBP7), tissue inhibitor of metalloproteinases-2 (TIMP-2); their levels in urine need to be monitored on urgent basis." (PMID 31750312, 2019). "Tissue inhibitor of metalloproteinase-2 (TIMP-2) and insulin-like growth factor binding protein 7 (IGFBP7) are recently identified urinary biomarkers of acute kidney injury (AKI) in critically ill patients." (PMID 31261582, 2019). "Fibroblast growth factor 23 (FGF23) and insulin-like growth factor binding protein 7 (IGFBP-7) are suggested to be biomarkers for predicting acute kidney injury (AKI)." (PMID 29907141, 2018). "Tissue inhibitor of metalloproteinase-2 (TIMP-2) and insulin-like growth factor-binding protein-7 (IGFBP7) are both involved in renal tubular epithelial cell cycle arrest in acute kidney injury (AKI)." (PMID 28107490, 2017). "Empagliflozin, an SGLT2 inhibitor, has shown renoprotective effects by reducing markers of acute kidney injury (AKI), including IGFBP7." (PMID 38255264, 2024). "Most previous studies have focused on IGFBP7 and TIMP-2 for their role in acute kidney injury (AKI) prediction." (PMID 35327386, 2022). "Kashani K’s study demonstrated that NAGL was weaker than NephroCheck and urinary TIMP-2/IGFBP7, but stronger than plasma cystatin C and urine KIM-1 in predicting acute kidney injury." (PMID 35887790, 2022). "The product of the concentrations of urinary tissue inhibitor of metalloproteinases-2 and insulin-like growth factor binding protein-7 (urinary [TIMP-2] × [IGFBP-7]) has been suggested as biomarker for early detection of acute kidney injury (AKI) in various clinical settings." (PMID 31315590, 2019). "Moreover, IGFBP7 is a urinary marker of cell-cycle arrest in the pathogenesis of acute kidney injury (AKI)." (PMID 26974954, 2016).
acute kidney injury (continued). "The recent discovery of cell cycle arrest biomarkers, tissue inhibitor of metalloproteinases (TIMP)-2 and insulin-like growth factor binding protein 7 (IGFBP7), has led to a newly available clinical test for acute kidney injury." (PMID 27245788, 2016). "It therefore seems very reasonable that cut-off values of urinary [TIMP-2] × [IGFBP7] for non-DGF are higher than those validated for the identification of acute kidney injury in critically ill adults." (PMID 38673754, 2024). "As one of the first gap cell cycle arrest biomarkers, urinary IGFBP7, multiplied with tissue inhibitor metalloproteinase-2, has been approved by FDA for the acute kidney injury prediction in patients who have acute cardiovascular or respiratory failure (Hasson, Menon & Gist, 2022)." (PMID 37304887, 2023). "It has been demonstrated that TIMP-2 and IGFBP7 are useful in predicting acute kidney injury following cardiac surgery, and compared with other biomarkers, TIMP-2 and IGFBP7 might be useful to predict the onset of severe AKI." (PMID 36313991, 2022). "The Nephrocheck® test is a single-use cartridge designed to measure the concentrations of two novel cell-cycle arrest biomarkers of acute kidney injury, namely tissue inhibitor of metalloproteinase 2 (TIMP-2) and insulin-like growth factor binding protein 7 (IGFBP7)." (PMID 35252280, 2022). "The aim of this study was to evaluate uCHI3L1 as a biomarker for AKI in ICU patients included in the multicenter Finnish Acute Kidney Injury (FINNAKI) study and compare this to the NephroCheck Risk® score, the composite of the cell cycle arrest biomarkers TIMP-2 and IGFBP7." (PMID 32276601, 2020). "Elevated urinary IGFBP-7 and TIMP-2 levels reflect acute kidney injury (AKI), renal tubular damage, and fibrosis common in MM due to plasma cell infiltration and light chain deposition." (PMID 40369504, 2025). "•The authors analysed the impact of propofol or sevoflurane anaesthesia on RIPC in reducing acute kidney injury (AKI) after cardiac surgery as reflected in the cell cycle arrest biomarkers TIMP-2 and IGFBP7 in urine." (PMID 41093687, 2025). "While it did not impact cardiac parameters, empagliflozin significantly reduced markers of acute kidney injury (AKI), specifically TIMP-2 and IGFBP7, indicating protection against tubular kidney damage." (PMID 38255264, 2024). "It is consistent with recent research, which has proven that IGFBP7, together with the tissue inhibitor of metalloproteinases-2 (TIMP-2), is a novel marker of tubular damage, and it can be used for the early detection of acute-kidney-injury (AKI)-endangered patients." (PMID 35204773, 2022). "For the detection of cardiac surgery-associated acute kidney injury (CS-AKI), the performance of urine tissue inhibitor of metalloproteinase 2 insulin-like growth factor-binding protein 7 (TIMP2 IGFBP7) has never been compared with that of very early changes in plasma creatinine (∆pCr)." (PMID 34641779, 2021). "However, IGFBP7 was recently shown to be a useful biomarker of acute kidney injury (AKI) even without explanation of the reasons for elevated urinary IGFBP7 levels." (PMID 26974954, 2016).